BRCA1 (BRCA1 DNA repair associated)
Diseases named in the same sentence as BRCA1 in open-access papers (continued):
Sharing a sentence is not in itself a finding about the gene and the disease.
prostate carcinoma (continued). "Germline mutations in these genes have been associated for a long time with breast and ovarian cancer hereditary syndrome, and more recently, pancreas and prostate cancers have also been linked to BRCA1/2-mutated cancer spectrum." (PMID 38544832, 2024). "For example, while olaparib has been FDA‐approved for metastatic CHEK2‐ and ATM‐mutated prostate cancer; therapeutic benefit in these patients was suboptimal in comparison to patients harboring BRCA1/2 mutations." (PMID 38898688, 2024). "In this paper, we reported, to the best of our knowledge, the first case of prostate cancer with cutaneous metastasis to the scalp owing to somatic BRCA1 mutation." (PMID 39465866, 2024). "Several PARP inhibitors have been approved by both the US Food and Drug Administration and the European Medicines Agency to treat patients with BRCA1/2-deficient ovarian, breast, and castration-resistant prostate cancers." (PMID 39730675, 2024). "The detection of somatic BRCA1/2 mutations is sufficient for the administration of PARPis in ovarian and prostate cancers." (PMID 38612902, 2024). "The proportion of BRCAm to HR mutated genes, besides BRCA1/2, for pancreatic and prostate cancer was 5–6% and 4–16%, respectively." (PMID 38184614, 2024). "We extracted total DNA from the prostate cancer tissue of the patient’s father and used it to screen for mutations in the BRCA1/2 and HRDscore genes." (PMID 39364320, 2024). "An improved understanding of individual risk would account for ethnicity, advancing age, family history of prostate cancer, and genetics (eg, mutations in BRCA1, BRCA2, ATM, and the mismatch repair genes)." (PMID 38583453, 2024). "Age-eligible male BRCA1/2 AF recipients (n=17) were recommended to discuss prostate cancer risk/screening with their GP or referred to urology." (PMID 38131308, 2024). "In the case of prostate cancer, BRCA1 and BRCA2 mutations would lead to 8.6% and 15% cumulative risks respectively by age of 65 years." (PMID 38274092, 2023). "In this report, we reaffirmed our previous findings that synchronous metastatic prostate cancers with BRCA1/2 mutations present with relatively low serum PSA levels but higher Gleason grade groups." (PMID 37568814, 2023). "BRCA1 increases the risk of prostate cancer in patients less than 65 years old by 1.8 fold and BRCA2 by 4.5 times." (PMID 36998466, 2023). "Early breast and prostate cancers share characteristics, including hormone dependence and BRCA1/2 mutations." (PMID 37965470, 2023). "The presence of BRCA1/2 mutations in breast and prostate cancer, as well as BRAF mutations in melanoma, are other examples where molecular profiling can impact cancer therapeutics." (PMID 37368872, 2023). "With respect to cancer therapy, PARP inhibitors are effective treatments for ovarian, breast, pancreatic, and prostate cancers with mutations in BRCA1 or BRCA2." (PMID 37492888, 2023). "Of the inherited prostate cancers, approximately 5.3% contain BRCA2 and 0.9% contain BRCA1 mutations making these subsets of prostate cancer ideal targets for PARP inhibitor therapy." (PMID 37035242, 2023). "HRD phenotypes in breast, ovarian, pancreatic, and prostate cancers have been associated with germline and somatic mutations as well as suppression of epigenetic modifications in BRCA1 and BRCA2." (PMID 37808268, 2023). "BRCA1 mutations have also been associated with increased prostate cancer risk, although with less magnitude of risk." (PMID 37240284, 2023). "BRCA1/2 mutations are not only associated with an increased risk of prostate cancer, but also with an aggressive prostate cancer phenotype, such as higher grade, advantaged stage, and poor survival." (PMID 36937425, 2023). "Recent genomic analytical advancements have revealed that BRCA1/BRCA2 pathogenic variants are the most frequent mutations among DDR genes in prostate cancer." (PMID 37174127, 2023).
prostate carcinoma (continued). "Patients must have confirmation of a PV in the BRCA1/BRCA2 prostate cancer susceptibility genes (germline or somatic) before initiating treatment with olaparib." (PMID 37240284, 2023). "Approximately 50% of BRCA1/2 mutations in prostate cancer are somatic lineage mutations; therefore, it is important to consider this when selecting diagnostic methods." (PMID 37174127, 2023). "Individuals harboring pathogenic variants in BRCA1/2 have an elevated lifetime risk of developing BC, OC, prostate cancer and pancreatic cancer." (PMID 35908255, 2023). "Numerous studies have highlighted the significant efficacy of PARP inhibitors in breast, ovarian, and prostate cancers with BRCA1/2 mutations." (PMID 37834477, 2023). "In prostate cancer, the frequencies of germline and somatic variants of BRCA1/BRCA2 are almost the same; therefore, evaluation of both germline and somatic variants is necessary." (PMID 37174127, 2023). "Recent genomic analytical advancements have revealed that BRCA1/2 pathogenic variants are the most frequent mutations among DNA damage repair genes in prostate cancer." (PMID 37174127, 2023). "PARP inhibitors have been approved for the treatment of ovarian, breast, pancreatic, and prostate cancers carrying deleterious BRCA1/2 pathogenic variants or homologous recombination repair (HRR) deficiency (HRD)." (PMID 35326540, 2022). "FDA-approved PARPi (olaparib, niraparib, rucaparib, and talazoparib) are the first synthetic lethal targeted drugs to enter clinical practice and are currently used to treat ovarian, breast, pancreatic, or prostate cancer characterized by BRCA1/2 mutations." (PMID 36612003, 2022). "Prostate cancers with germline BRCA1 or BRCA2 mutations tend to be more aggressive than those without these mutations." (PMID 36551924, 2022). "PARP inhibitors are used for the treatment of BRCA1/2-deficient breast, ovarian, and prostate cancer." (PMID 36350633, 2022). "We observed higher mRNA expression levels, especially for the mitotic factors identified at stressed replication forks in breast and prostate cancer patients with BRCA1/2 mutations compared to the respective BRCA1/2 wild-type cancers." (PMID 36350633, 2022). "GJB2, MET, MUTYH and VHL mutations ranked top in kidney cancers, and ATM and CHEK2 mutations ranked top for bladder cancer, while ATM and BRCA1 mutations ranked top for prostate cancer." (PMID 36451132, 2022). "We assessed the associations of these PRS with breast and prostate cancer risks for male BRCA1 and BRCA2 pathogenic variant carriers." (PMID 34320204, 2022). "PARP inhibitors are approved in breast, ovarian, pancreatic, and prostate cancers harbouring a pathogenic variant in BRCA1 or BRCA2, where PARP1 inhibition results mainly in synthetic lethality in cells with impaired homologous recombination." (PMID 35681784, 2022). "BRCA1-mutated prostate cancer has been shown to be less responsive to poly (ADP-ribose) polymerase (PARP) inhibitors as compared to BRCA2-mutated prostate cancer." (PMID 36185208, 2022). "BRCA1/BRCA2/ATM mutations were the first reported molecular alterations conferring sensitivity to PARP inhibitors in prostate cancer and are the most widely studied germline and somatic mutations in this setting." (PMID 35448200, 2022). "It is estimated that BRCA1 mutations increase prostate cancer risk by 1.8 to 3.5 times and BRCA2 by 4.6 to 8.6 times." (PMID 36294924, 2022). "BRCA1 is known as a tumor suppressor as mutations in this gene confer an increased risk for breast, ovarian, and prostate cancers." (PMID 36012562, 2022). "PARP inhibitors are actually approved in breast, ovarian, pancreatic and prostate cancers harbouring a pathogenic or likely pathogenic variant in BRCA1 or BRCA2 (BRCA1/2)." (PMID 35681784, 2022). "As for prostate cancer, the addition of the genes included in this review to BRCA1 and BRCA2 more than doubles the mutational burden in both germline and in somatic sample PVs (8.6% to 20.7% and 15.2% to 36.9%)." (PMID 35563100, 2022).
prostate carcinoma (continued). "We recommend that all Chinese diagnosed with breast, ovarian, pancreatic or prostate cancers and also healthy family members, shall undergo BRCA1/2 gene test to provide risk assessment." (PMID 36439508, 2022). "BRCA1/2 mutations play a significant role in cancer pathogenesis and predisposition particularly in breast, ovarian and prostate cancers." (PMID 35753294, 2022). "In prostate cancer, BRCA1/2 mutations represent around 13% of the of DDR genes alterations in tumor samples and 51% of all germline variants found in individuals affected by prostate cancer, with BRCA2 harboring the majority of variants." (PMID 35563100, 2022). "The current study attempts to elucidate the molecular mechanism of differential response to PARP inhibitors in men with advanced prostate cancer harboring BRCA1 versus BRCA2 mutation." (PMID 36185208, 2022). "In patients with prostate cancer, germline pathogenic BRCA1/2 variants are usually correlated with poor prognostic characteristics (aggressiveness, castration resistance, lymph node invasion and metastasis at diagnosis, and decreased overall survival)." (PMID 35448200, 2022). "We evaluated the associations of the most recently developed breast and prostate cancer PRS with site-specific cancer risks in the largest case-control study of male BRCA1 and BRCA2 carriers available to date." (PMID 34320204, 2022). "Other genes implicated in the development of prostate cancer include those involved in Homologous Recombination DNA repair: BRCA1 in 199452, CHEK2 in 200353,54, ATM in 200455, and PALB2 in 200856." (PMID 35732815, 2022). "We observed a high level of BRCA1 germline mutation in prostate cancer of NG and men of African ancestry." (PMID 36922933, 2022). "To test this, we extracted gene expression levels for 65 proteins that were proximal to PARP1 and present at stressed replication forks, from breast, ovarian, and prostate cancer samples with wild-type or mutated BRCA1 or BRCA2 from the cBioPortal." (PMID 36350633, 2022). "A recent prospective study of prostate cancer risk found men who carry a BRCA1 mutation have an absolute risk for prostate cancer of 21% to age 75 and 29% to age 8566." (PMID 35732815, 2022). "A recent prospective study estimated the lifetime risk of developing prostate cancer to be 29% for BRCA1 and 60% for BRCA2 carriers." (PMID 34320204, 2022). "The phase I/II PETRA trial evaluated AZD5305 as monotherapy in patients with advanced metastatic breast, pancreatic, or prostate cancer with germline BRCA1, BRCA2, PALB2, or RAD51C mutations." (PMID 36010882, 2022). "PRSPC was associated with prostate cancer risk for BRCA1 (OR = 1.73, 95% CI = 1.28 to 2.33) and BRCA2 (OR = 1.60, 95% CI = 1.34 to 1.91) carriers." (PMID 34320204, 2022). "Parallel cell line generation of isogenic gene knockouts in ovarian and prostate cancer cell lines identified that inactivation of core HRR factors is required for driving in vitro PARPi responses comparable with the ones observed for BRCA1 or BRCA2 mutations." (PMID 36969741, 2022). "The medical consequences of a pathogenic germline variant for prostate cancer patients are mainly limited to patients with metastatic castration-resistant prostate cancer who carry a pathogenic variant in the BRCA1 or BRCA2 gene." (PMID 36581909, 2022). "PARP inhibitors (PARPi) are currently indicated for the treatment of ovarian, breast, pancreatic, and prostate cancers harboring mutations in the tumor suppressor genes BRCA1 or BRCA2." (PMID 36969741, 2022). "The PRSER+ and PRSPC odds ratios with breast or prostate cancer risks appeared to be larger for class II variant (pathogenic variants likely to yield stable mutant proteins) carriers compared with class I BRCA1 and BRCA2 variant carriers." (PMID 34320204, 2022).
prostate carcinoma (continued). "The interaction of TPX2 with HR proteins and the observation that TPX2 mRNA levels are upregulated in breast and prostate cancers with BRCA1/2 mutations, suggested a role of TPX2 in the repair of DSBs arising from collapsed replication forks by HR." (PMID 36350633, 2022). "BRCA1_rs799917 T>C has not previously been associated with prostate cancer; however, BRCA1 germline mutations contribute to increased prostate cancer risk and are associated with higher prostate cancer aggression and poorer outcomes." (PMID 36922933, 2022). "The risk of prostate cancer by the age of 69 is 6%, while with BRCA1 mutations, it rises to 8.6% by the age of 65." (PMID 35303741, 2022). "Similar to olaparib, rucaparib was approved by the FDA—but not by the EMA—for the treatment of metastatic castration-resistant prostate cancer patients with germline and/or somatic BRCA1/2 mutations, who progressed on AR signaling inhibitor or taxane." (PMID 36010882, 2022). "The increasingly wide use of PARP inhibitors in breast, ovarian, pancreatic, and prostate cancers harbouring a pathogenic variant in BRCA1 or BRCA2 has highlighted the problem of resistance to therapy." (PMID 35681784, 2022). "Our findings showed that these PRS, developed using population-based data, are associated with breast and prostate cancer risks for male BRCA1 and BRCA2 carriers." (PMID 34320204, 2022). "For example, ERBB2 alterations co-segregate strongly with BRCA1 and are known to be associated with tumor aggressiveness in primary prostate cancer, tumor progression and invasion in advanced prostate cancer, and shorter time to castration-resistance." (PMID 36185208, 2022). "Whole-exome and transcriptome profiling of 150 metastatic castration-resistant prostate cancer found that more than 19% of them have at least one mutation in BRCA1, BRCA2, ATM and CDK12." (PMID 36371386, 2022). "Lifetime prostate cancer risk in males with BRCA1 alteration carriers is thought to be similar to that of the general population, but is approximately 20% for those with BRCA2 alterations." (PMID 35933387, 2022). "The combination of prostate cancer and colon cancer share both genetic risk factors such as the BRCA1/BRCA2 mutation and dietary ones." (PMID 34556087, 2021). "Mutations of the BRCA1/2 gene are associated with a higher risk of certain tumors, including prostate cancer." (PMID 34298770, 2021). "The most common mutations involved in prostate cancer include BRCA1/2; ATM (odds ratio (OR) = 2.18), HoxB13 (OR = 3.23), genes involved in repairing mismatched genes and genes associated with Lynch Syndrome (OR = 4.87), and CHEK2 (OR = 1.98)." (PMID 33937056, 2021). "The carriers of BRCA1/2 mutations have a high risk of specific cancer, such as breast, ovarian, pancreatic, and prostate cancer." (PMID 34356066, 2021). "It has been highlighted that BRCA1/2 mutation carriers present an increased risk for prostate cancer (3.4-fold in BRCA1, 8.6-fold in BRCA2)." (PMID 33484353, 2021). "Germline mutations in BRCA2 and BRCA1 are associated with increased incidence and aggressiveness of prostate cancer, and have been identified as biomarkers for platinum therapy and PARP inhibitors." (PMID 33625671, 2021). "A study has shown a 1.2% prevalence rate of pathogenic BRCA1/2 variants in unselected prostate cancer patients." (PMID 34082720, 2021). "The IMPACT study (Identification of Men with a Genetic Predisposition to Prostate Cancer: Targeted screening in germline BRCA1/2 mutation carriers and controls) facilitated annual PSA screening in families with germline BRCA1/2 mutations." (PMID 34884434, 2021). "A recent meta-analysis revealed that the relative risk of prostate cancer is 1.35-fold and 2.64-fold in BRCA1 and BRCA2 carriers, respectively." (PMID 34356066, 2021). "For example, in a study of 913 male carriers of germline BRCA1 mutation, the relative risk of prostate cancer was increased by 3.75-fold with an 8.6% cumulative risk by the age of 65." (PMID 34884434, 2021).
prostate carcinoma (continued). "Similar indications for OC treatment are formulated for rucaparib; rucaparib is also recommended for pretreated prostate cancers carrying germ-line or somatic BRCA1/2 mutations." (PMID 34454564, 2021). "In advanced prostate cancer patients with BRCA1/2 or ATM mutations, poly (ADP-ribose) polymerase inhibition (PARPi) causes an increased overall survival advantage compared with patients without these mutations." (PMID 34712892, 2021). "Thereby, the aim of this study was to characterize and to estimate the prevalence of germline BRCA1/2 mutations and large rearrangements in Moroccan patients with familial prostate cancer." (PMID 34242281, 2021). "The National Comprehensive Cancer Network prostate cancer guideline recommends genetic counseling for patients with prostate cancer and having BRCA1/2, ATM, PALB2, or FANCA mutation." (PMID 31931827, 2020). "Emerging data has also linked several germline DNA mutations to prostate cancer, namely BRCA1, BRCA2, MSH, ATM, PALB2, CHEK2, and MUTYH." (PMID 32957584, 2020). "The application of PARP inhibitors in the treatment of prostate cancer was initiated in 2015 following the finding that 19.6% of prostate cancers had BRCA1, BRCA2 or ATM mutations." (PMID 33015058, 2020). "There are currently several PARP inhibitors approved for the treatment of BRCA1/2 mutated breast, ovarian, pancreatic and prostate cancers." (PMID 33015058, 2020). "Looking into BRCA1, a study of 813 cases of prostate cancer found that having BRCA1 germline mutations resulted in a 3.75-fold relative risk for developing prostate cancer and in a cumulative risk of 8.6% of developing prostate cancer by 65 years old." (PMID 32197306, 2020). "Due to the relatively low frequency of BRCA1/2 mutations, this limits their applicability to the treatment of 10–15% of breast and ovarian tumors, 4–7% of pancreatic tumors and 1.5% of prostate carcinoma." (PMID 33015058, 2020). "Currently, the IMPACT study is being conducted to aid the development of early detection guidelines for prostate cancer in men with BRCA1/2 germline mutations." (PMID 32197306, 2020). "Although all the PARPi under development have shown single-agent activity for BRCA1/2-mutated prostate cancer, the efficacy and safety profiles seem to correlate their potency in PARP trapping when PARPi are being combined with abiraterone." (PMID 31404966, 2019). "Eight BRCA2-mutated prostate cancer patients and eight BRCA1/2 wild-type patients matched for age, Gleason score, initial PSA, and initial TNM state were selected for this retrospective analysis." (PMID 31549213, 2019). "In this phase I trial, 60 patients with castration-resistant prostate cancer, carrying BRCA1/2 mutations and refractory to standard therapies, were treated with escalating doses of Olaparib." (PMID 31242618, 2019). "In a further analysis, high rates of prostate cancer progression from localized to systemic disease were observed in a cohort of patients carrying germline mutations in the BRCA1/BRCA2 genes (n = 79)." (PMID 31242618, 2019). "Prostate cancer patients who have mutations in the DNA repair pathway (such as BRCA1, BRCA2, ATM, RAD51D and PALB2) have been shown to be significantly more likely to have advanced disease than patients without these mutations." (PMID 31915536, 2019). "Results show an increased number of tumor-infiltrating lymphocytes, including potentially immunosuppressive FOXP3-positive lymphocytes, in BRCA2-mutated prostate cancers compared to the BRCA1/2 wild-type group, which harbored mostly extratumoral immune cells." (PMID 31549213, 2019). "BRCA1 mutation carriers increase the risk of prostate cancer in men aged < 65 years by 3.8-fold, and germline mutations in the BRCA2 gene increase prostate cancer risk by 8.6-fold." (PMID 31477094, 2019).